HMGB1P45 (high mobility group box 1 pseudogene 45)
Gene: Processed pseudogene on chromosome 1 (50,398,825 to 50,399,773, reverse strand). Ensembl gene ENSG00000229316.
Diseases named in the same sentence as HMGB1P45 in open-access papers:
HMGB1P45 is named in the same sentence as 1 disease in open-access papers, as found by Europe PMC text mining. Sharing a sentence is not in itself a finding about the gene and the disease. The quoted sentences say what the papers report.
Headache (1 paper, 2022). Cephalgia, or pain sensed in various parts of the head, not confined to the area of distribution of any nerve. "Of the genes at these loci, six (FAF1, TMX2-CTNND1, AARSD1, PLCD3, ZNF652, and C20orf203; headache-TSH) and six (HMGB1P45, RPL30P1, ZNF462, TMX2-CTNND1, ITPK1, SECISBP2L; headache-fT4) were significant in our gene-based analysis (pFisher’s combined p-value < 2.09 × 10−6)." (PMID 36672757, 2022).